BCL2 (BCL2 apoptosis regulator)
Diseases named in the same sentence as BCL2 in open-access papers (continued):
Sharing a sentence is not in itself a finding about the gene and the disease.
colorectal cancer (continued). "Down-regulation of miR-1915-3p was responsible for multidrug resistance in colorectal cancer, and re-establishing miR-1915-3p could restore the chemosensitivity depend on suppression of BCL-2 and NFIX expression." (PMID 34774019, 2021). "It has been reported that PGE2 inhibited Bcl-2 mediated programmed cell death in colorectal cancer." (PMID 34093801, 2021). "Within colorectal cancer cells, BCL2 is well known to act to suppress the induction of apoptosis." (PMID 33469000, 2021). "Moreover, it was shown that PPAR δ agonists (rosiglitazone) sensitizes colorectal cancer cells to 5-FU by downregulation of Bcl-2 proteins and upregulation of Bax." (PMID 31936346, 2020). "Our finding indicates that PT inhibited Bcl2 and BclxL protein expression in various colorectal cancer cells indicating that PT may alter NFkB and STAT3 pathway." (PMID 32703189, 2020). "Moreover, honokiol radiosensitizes colorectal cancer cells due to higher levels of apoptosis (caspase-3 activation, increased Bax/Bcl-2 ratio) and reduced expression of cyclin A1 and D1." (PMID 31936346, 2020). "Overall, we clearly show that a combination treatment targeting the MEK- and PI3K-pathways is insufficient to block the acquisition of resistance in human colorectal cancer cell line models, but the addition of a third agent, a BCL2 inhibitor, is able to do this." (PMID 30905967, 2019). "In addition, it has been reported that inhibition of the PI3K/Akt/mammalian target of rapamycin (mTOR) pathway by apigenin enhances Bax expression and suppresses Bcl-2 expression and tumor cell growth in cisplatin-resistant human colorectal cancer cells." (PMID 31769426, 2019). "Expression of Bax and Bcl-2 proteins may be helpful in predicting clinical outcome, patients survival, and response to chemotherapeutic agents in colorectal carcinoma." (PMID 31861952, 2019). "Overexpression of HSP20 in HCT-116 human colorectal cancer cells induced massive apoptosis in a time-dependent manner by enhancing caspase-3/7 activity and downregulating mRNA and proteins levels of anti-apoptotic Bcl-xL and Bcl-2." (PMID 30286088, 2018). "The bax/bcl-2 ratio, representing the proportion of apoptosis promotion to inhibition, may be a positive prognostic marker in colorectal cancer patients." (PMID 30557404, 2018). "As a proto-oncogene, Bcl2 inhibits cell apoptosis in the cancer development that is widely expressed in various malignancies such as lung, breast, prostate, and colorectal cancer, which plays a critical role in maintenance of normal tissues homeostasis and uncontrolled cell proliferation." (PMID 30519260, 2018). "Similarly, in an experiment using conditionally reprogramed cells derived from colorectal cancer patients, synergistic growth inhibition was observed in cells with low Bcl-2 expression." (PMID 30420612, 2018). "The anti-apoptotic Bcl2 protein has been demonstrated to be overexpressed in colorectal cancers." (PMID 28049506, 2017). "Whether expression levels of Bcl-2 and Bax actually correlate with response to chemotherapy is as yet uncertain, as shown in breast and colorectal cancer." (PMID 28098760, 2017). "Even a report has indicated that rs7911488 C-allelic pre-miR-1307 binds to MBNL1 and infers with Dicer processing, and then leads to the decreased miR-1307 and increased Bcl-2 expression, thus representing an important process in the initiation of colorectal cancer." (PMID 28086946, 2017).
colorectal cancer (continued). "In addition, increased expression of genes that favor apoptosis (Bax, and Bak) and a reduced expression of counter-players that prevent apoptosis (Bcl-2, and Bcl-XL) were all reported to be the molecular mechanisms of SCFAs that mediate colorectal cancer." (PMID 28230723, 2017). "In colorectal cancer samples and miR-139-5p mice, the expression levels of miR-139-5p were inversely correlated with BCL2 expression, which suggested that miR-139-5p in colorectal cancer acted as a strong tumour suppressor by regulating the invasiveness and drug resistance." (PMID 27244080, 2016). "To determine whether the role of miR-139-5p in colorectal cancer is mediated by BCL2, we overexpressed BCL2 in miR-139-5p-transfected HCT116 and SW620 cells." (PMID 27244080, 2016). "MiR-1915 targets BCL-2 and modulates multidrug resistance of human colorectal carcinoma cells." (PMID 27144561, 2016). "In conclusion, PXN promotes Bcl-2 phosphorylation at Serine 87 via PXN-mediated ERK activation, and its stabilization associated with increased tumor formation efficacy in mice and poor patient outcome in colorectal cancer patients." (PMID 25826088, 2015). "CARMA3 and Bcl-2 are direct targets of miR-195 in colorectal cancer." (PMID 26650737, 2015). "Therefore, the aim of this study was to further dissect the anti-cancer properties of obatoclax in colorectal cancer cells and to further elucidate the contribution of antiapoptotic Bcl-2 proteins in the crosstalk between apoptosis and autophagy." (PMID 26585594, 2015). "We next examined whether PXN, Bcl-2, pBcl-2-S87, and MMP2 expression could be associated with the outcomes of patients with colorectal cancer." (PMID 25826088, 2015). "We examined the possibility that PXN expression could be associated with Bcl-2, pBcl-2-S87, and MMP2 expression in tumors from 190 colorectal cancer patients." (PMID 25826088, 2015). "It was reported that the over-expression of Bcl-2 in human cervical and colorectal carcinoma cells resulted in an increased telomerase activity and a resistance to apoptosis, indicating a link between Bcl-2 expression and telomerase activity in human cancer cells." (PMID 25880193, 2015). "In conclusion, our data revealed that pan-Bcl-2 inhibitor Obatoclax exerts various antitumor activities independent of cell death induction, recommending pan-Bcl-2 inhibition for further clinical development in colorectal cancer." (PMID 25192188, 2014). "MiR-195 could also promote colorectal cancer cell apoptosis and suppress tumorigenicity by targeting BCL-2." (PMID 22723898, 2012). "BCL-2 expression was found to be more often positive in S. mansoni-associated colorectal cancers (58.3% versus 33.3% in nonschistosomal colorectal cancers, P = 0.046)." (PMID 22174720, 2011). "The upregulation of Bcl-2 in colorectal cancer is well established by various investigators." (PMID 19703310, 2009). "Moreover, it was reported that circulating BCL2 in colorectal cancer (CRC) cases may represent the quantity of BCL2 expression in cancer tissue and could be effective as a predictive diagnostic in CRC62." (PMID 40730640, 2025).
colorectal cancer (continued). "Curcumin showed promising results on colorectal cancer stem cells by the down-regulation of irinotecan/5-FU chemoresistance, decreased tumor sphere formation, the increased activity of Bax proteins, caspase-3, -8, -9 and decreased activity of the Bcl-2 protein." (PMID 39859345, 2025). "In addition, the essential oil exhibited pronounced antitumor effects, particularly against HCT116 colorectal cancer cells, in which it induced apoptosis through modulation of Bax, Bcl-2, and caspase-3 expression, and triggered G1-phase cell-cycle arrest via downregulation of Cyclin D and p-AKT." (PMID 40650258, 2025). "Moreover, BAX levels increased and BCL-2 levels decreased both lung and colorectal cancer cells." (PMID 39838121, 2025). "The extent to which DAC potentiates CPT-11 or SN-38 might be dependent on the expression level of anti-apoptotic Bcl-2 protein in human colorectal cancer cells, as the higher intracellular protein levels of Bcl-2 were shown to be associated with the resistance of cancer cells to CPT-11 and SN-38." (PMID 37092854, 2023). "Similarly, Curcumin treatment of a colorectal cancer cell line has been demonstrated to regulate the NFκβ pathway, suppressing the expression of key regulatory genes involved in cell survival and cell cycles, such as cyclin D1, Bcl-2, VEGF, and MMP9." (PMID 36835252, 2023). "A recent paper demonstrated in a colorectal carcinoma (CRC) model that the YAP/TEAD complex binds to upregulate Bcl-2 expression, which leads to autophagy inhibition." (PMID 35053542, 2022). "Therefore, in order to further study the mechanism of RES and VE in promoting colorectal cancer cell apoptosis, western blotting was performed to detect the expression of BCL-2, BAX, caspase-3-, caspase-8-, and caspase-9-related proteins after RES and VE intervention." (PMID 34803703, 2021). "Consequently, Bax hyperexpression and Bcl-2 hyperexpression may explain the inductive effect of Dkk3 in apoptosis of colorectal cancer cells." (PMID 33425757, 2020). "The chloroform extract of H. diffusa Willd could significantly inhibit the cell growth and induced apoptosis by downregulating the expressions of antiapoptotic Bcl-2 and survivin and upregulating the expression of proapoptotic Bcl-2-X in colorectal cancer SW620 cells." (PMID 31354479, 2019). "Indeed, the overexpression of Bcl-2, Bcl-XL, Bcl-w, and Mcl-1 in different cancers, including glioma, neuroblastoma, melanoma, squamous carcinoma, and breast, lung, and colorectal cancer cells, leads to significant increase in their migratory and invasive properties." (PMID 31921862, 2019). "In addition, Bcl-2 protein stability by PXN overexpression may partially contribute to PXN-mediated invasion and consequently to cause poorer survival in colorectal cancer patients who received 5-FU-based chemotherapy." (PMID 25826088, 2015). "The aim of the study was to determine the relative level of mRNA expression of Bax and Bcl-2 genes and Bax/Bcl-2 ratio in tumoral tissues and adjacent non-tumoral tissues, and to evaluate the correlation between Bax/Bcl-2 ratio and clinicopathological parameters of colorectal carcinoma." (PMID 25864810, 2015). "Thus immunohistochemical bcl-2 phenotyping of colorectal carcinoma may contribute in future to the clinical management of these patients." (PMID 7547253, 1995).
colorectal cancer (continued). "In this study, we focused on examining the effects of Warbugia ugandensis (W. ugandensis) methanolic root and stem infusions on the activity of five target genes—COX-2, CASPS-9, Bcl-xL, Bcl2, and 5-LOX—using colorectal cancer (CRC) cell lines (Caco-2)." (PMID 39940328, 2025). "For this purpose, the relative expression of CASP3, CASP9, BCL2, and BCL2L11 was quantified in colorectal cancer DLD-1 and SW620 cells treated with 7 mg/mL of the extract for 72 h." (PMID 40298626, 2025). "In colorectal cancer (CRC), B7-H3 has been found to promote Jak2-STAT3 signaling, which increases the expression of the anti-apoptotic proteins Bcl-2 and Bcl-xl." (PMID 40214484, 2025). "For instance, the methanolic extract of Artemisia absinthium induced apoptosis in colorectal cancer through MMP destruction and elevation in BAX/Bcl-2 ratio and caspase-3 expression." (PMID 38966207, 2024). "The EGFR-directed QDMs containing Bcl2 siRNA, so-called immuno-QDM/siBcl2 (iQDM/siBcl2), exhibited the more effective delivery of QDs and siBcl2 to target human colorectal cancer cells in cultures as well as in mouse xenografts." (PMID 38892434, 2024). "Extracellular vesicles produced by L. paracasei (LpEVs) have been demonstrated to reduce colorectal cancer cell proliferation and induce apoptosis through the PDK1/AKT/Bcl-2 pathway." (PMID 38326490, 2024). "In line with our findings, co-inhibition of MCL-1 and BCL-xL showed stronger cytotoxicity in many sarcomas and other cell lines, including those derived from colorectal cancer (CRC) and cervical cancer, compared to co-inhibition of BCL-2/BCL-xL or MCL-1/BCL-2." (PMID 39497108, 2024). "Nisin, a bacteriocin produced by Lactococcus lactis, was shown to induce apoptosis in colorectal cancer cells by increasing the expression of pro-apoptotic protein BCL-2, shifting the BAX/BCL-2 apoptotic index." (PMID 38792785, 2024). "To further explore the effect of 23-HBA inhibition of IL-10 release from M2 macrophages on chemotherapy resistance in colorectal cancer, we conducted an analysis of STAT3 and Bcl-2, both of which serve as key mediators within the IL-10 signaling pathway." (PMID 38554148, 2024). "In HCT116 and SW480 colorectal cancer cells, inhibiting phosphorylated p38 MAPK reduces the Bcl-2 expression." (PMID 37185746, 2023). "A further in vitro study conducted on a human colorectal cancer cell line LS180 demonstrated that HT is able to induce apoptosis, enhancing CASP3 gene expression and the BAX:BCL2 ratio." (PMID 38255664, 2023). "In contrast, knockdown of CD155 in colorectal cancer cells inhibited tumor cell proliferation, invasion, and conversely induced apoptosis via AKT/Bcl-2/Bax." (PMID 37441080, 2023). "Quercetin and kaempferol have many of the same targets, such as AKT1, AHR, BCL2, NR4A1, etc., and AHR can inhibit the development of colorectal cancer 119-121." (PMID 37497415, 2023). "The objective of this study was to analyze and evaluate the efficacy of Aloe secundiflora’s (AS) methanolic extracts on the expression of CASPS9, 5-LOX, Bcl2, Bcl-xL, and COX-2 in colorectal cancer (CRC) management." (PMID 37894369, 2023). "One study demonstrated that sorbitol induces apoptosis in colorectal cancer cells by increasing the phosphorylation of p38 MAPK, upregulating the expression of BAX and cleaved caspase-3 while downregulating the expression of Bcl-2." (PMID 37185746, 2023). "Further, they can inhibit the growth of colorectal cancer cells in vivo and in vitro by inducing apoptosis through the 3-phosphoinositide-dependent protein kinase-1 (PDK1)/AKT/Bcl-2 signaling pathway." (PMID 36613399, 2023).
colorectal cancer (continued). "In colorectal carcinoma, IGF2BP3 has been shown to activate the MEK1/ERK signaling pathway and promote anti-apoptotic pathways through the stabilization of Bcl-2 and Bcl-xL transcripts." (PMID 37760460, 2023). "Camphor and eucalyptol have demonstrated the induction of apoptosis through the down-regulation of anti-apoptotic factor BCL-2 in a human oral epidermoid carcinoma cell line and activation of the CASPASE cascade in oral KB and colorectal cancer cell lines." (PMID 35009072, 2021). "The Western blot assay was used to determine the changes of apoptosis-related proteins Bax, Bcl-2, PARP, and Cleaved-PARP after treatment of colorectal cancer SW480 and SW1116 cells with ivermectin at the indicated doses." (PMID 34483925, 2021). "LncRNA CASC2 silences BCL2 expression through EZH2-dependent binding to the promoter region of BCL2, thus enhancing the cytotoxicity of berberine-induced colorectal cancer cells." (PMID 34888249, 2021). "In colorectal cancer (HCT116 and HT29) cell lines, TSA induces the expression of Bax and decreases the expression of Bcl-2 and Bcl-xL." (PMID 34659660, 2021). "In this study we found that PT inhibited the expression of Bcl2, BclxL and XIAP in colorectal cancer cells." (PMID 32703189, 2020). "In addition to BCL2, potent and highly selective small molecule inhibitors of its relatives, BCLxL and MCL1, are now available, prompting us to investigate the susceptibility of colorectal cancers to the inhibition of one or more of these pro-survival proteins." (PMID 32913182, 2020). "Hence, BCL2 may be a valuable prognostic-predictive marker in colorectal cancer." (PMID 32883271, 2020). "STAT5 is reported to influence the expression of Bcl-2, Survivin, MMP-2, MMP-9, VEGF, and E-cadherin by interacting with MAPK pathway in colorectal cancer cells." (PMID 30847297, 2019). "Interplay between Bcl-2 and the p110α subunit of PI3K regulates human colorectal cancer cell migration through actin polymerization and filopodia formation." (PMID 31921862, 2019). "In colorectal cancer (CRC), SPARC can function as a sensitizer to conventional chemotherapy by enhancing apoptosis by interfering with the activity of Bcl-2." (PMID 31243264, 2019). "The first aim was to obtain evidence for the actual expression of Bcl2, Bad, BAX, caspase-8, and caspase-9 in pancreatic and colorectal carcinoma cells." (PMID 30686270, 2019). "Intriguingly, depletion of antiapoptotic BCL-2 proteins such as BCL-2, BCL-xL, and MCL-1 in colorectal cancer cells fail to suppress cell proliferation." (PMID 28035994, 2016). "Lactobacillus reuteri was shown to prevent colorectal cancer via downregulating NF-kB-dependent gene products that regulate cell proliferation (COX-2, cyclin D1) and survival (Bcl-2, Bcl-xL)." (PMID 26849051, 2016). "Introduction of S. crispus ethanol extracts before AOM seems beneficial in retarding colorectal cancer formation by preventing cell proliferation and inhibiting the activation of PCNA and Bcl2." (PMID 26307342, 2015). "In the present study, we provided the evidence that the stabilization of Bcl-2 by its phosphorylation at Serine 87 via PXN-mediated ERK activation promoted tumor invasion and poor patient outcome in colorectal cancer." (PMID 25826088, 2015). "Cox regression analysis of PXN, Bcl-2, pBcl-2-S87 and MMP2 expressions in patients with colorectal cancer." (PMID 25826088, 2015).